RNU6-1040P (RNA, U6 small nuclear 1040, pseudogene)
Gene: Small nuclear RNA gene on chromosome 8 (84,665,759 to 84,665,865, reverse strand). Ensembl gene ENSG00000206701.
Homologues: Orthologues: chimpanzee U6 (98% identical), macaque U6 (94% identical), rat LOC120093916 (74% identical). Paralogues in human: RNU6-140P (91% identical), RNU6-1316P (90% identical), RNU6-1031P (89% identical), RNU6-16P (89% identical), RNU6-536P (89% identical), RNU6-144P (88% identical), RNU6-20P (88% identical), RNU6-35P (88% identical), RNU6-434P (88% identical), RNU6-73P (88% identical), RNU6-756P (88% identical), RNU6-1124P (87% identical), and 1286 more.